IFIT1 (interferon induced protein with tetratricopeptide repeats 1)
Diseases named in the same sentence as IFIT1 in open-access papers (continued):
Sharing a sentence is not in itself a finding about the gene and the disease.
infection (continued). "Similar to what we observed with poly(I:C) stimulation, the NEMO-KD cells were still able to mount a full induction of IFIT1 and CXCL10 expression upon HAV infection, with only a slight decrease for CXCL10 at 48 h post infection." (PMID 39853114, 2025). "Upon infection of IFN-pre-treated A549 cells, very few cells express detectable mCherry, but knockout of IFIT1 is sufficient to restore viral gene expression to levels seen in the absence of IFN." (PMID 40146622, 2025). "We identified 6 genes found to be common in all three levels of infection whose expression level increases withthe increase in the level of infection (OASL, IFI27, IFIT1, IFIT3, RSAD2, IFI44L)." (PMID 40255307, 2025). "Despite this slower replication, and in contrast to CVB3–2Awt, infection with CVB3–2Amut resulted in significant induction of IFN-β and IFIT1 gene transcription, from 6 hpi onwards." (PMID 40875754, 2025). "The results showed that RSAD2 and IFIT1 effectively distinguished HPV16 infection from healthy controls and GV infection from untreated controls (AUC > 0.7), indicating significant diagnostic potential." (PMID 40510586, 2025). "RT-qPCR analysis of RNA isolated from hGBOs at 48 h post-infection revealed a robust upregulation of IFNB1 and IFNB1-stimulated IFIT1, MX1, CXCL10, and OAS1." (PMID 41255708, 2025). "Primary murine astrocytes significantly upregulated both IFIT-1 and IFIT-3 at 24 hours post-infection in response to N. meningitidis and S. pneumoniae across all tested MOIs." (PMID 41341589, 2025). "IFNB1 and IFIT1 transcription, as well as EMCV RNA replication, were quantified by RT-qPCR 7 h after infection." (PMID 40450684, 2025). "According to the previous study, the identified 6 genes were found to be common in all three levels of infection whose expressionlevel increases with the increase in the level of infection (OASL, IFI27, IFIT1, IFIT3, RSAD2 and IFI44L)." (PMID 40322700, 2025). "Despite BA.4 and BA.5 replicating similarly to BA.2 in HAEs, we consistently observed reduced innate activation, measured by ISG induction, after BA.4 and BA.5 infection (IFNB, CXCL10, IFIT1, IFIT2, DDX58 and RSAD2)." (PMID 38228858, 2024). "The 17 DEGs upregulated after infection with huH1N1 were shared with the swH1N1 infection (DDX58 (RIG-I), RSAD2 (Viperin), MX2, MX1, OAS1, ANGPTL4, IRF7, ISG15, IFIT1, ISG12(A), DDX60, BST2, IFI44, XAF1, LGALS3BP, RTP4, and IFI6)." (PMID 39247193, 2024). "Immune response genes such as the pro-inflammatory cytokine CXCL10, IFI27, USP18, IFIT1, and RSAD2/Viperin were shared between both in vivo infection times and A549 cells." (PMID 39065267, 2024). "Infection of macrophages for 24 h at 34°C with ts SeV-Cas9 induced less IFNB1 and IFIT1 expression compared to WT SeV-Cas9, which is in agreement with our findings in 293T cells." (PMID 39494910, 2024). "IFIT1 and IFIT5 possess the capability to detect uncapped viral triphosphate-RNA, which is an additional indicator of infection." (PMID 39303913, 2024). "Similar to previous reports, the expression levels of IFIT1, IRF1, and MX1 in Znfx1–/– BMDMs were higher than those in WT BMDMs following H37Rv infection, despite the increased intracellular M. tuberculosis burden in Znfx1–/– BMDMs." (PMID 38016036, 2024). "Consistently, knockdown of PCGF3 increased the expression levels of ISGs (ISG15, IFIT1, OAS2, MX1 and IRF7) and IFNB1, and decreased the VSV replicates (RNA level and virus titer) after VSV infection." (PMID 39368978, 2024). "Knockdown of DCAF7 had a relatively minimal effect on suppression of IFI6, IFIT1, OAS1&2 while affecting IFIT2 slightly more with HAdV-B7 infection." (PMID 38940561, 2024). "IFIT1, IFIT2 and ICP27 proteins were upregulated and, consistent with previous results, citrullinated following infection with HSV-1, especially at 16 hpi." (PMID 38055760, 2023). "Endogenous mRNA levels of the IFN-α, IFN-β and interferon-stimulated genes, IFIT1 and MX1, were measured at 0, 12, and 24 h post-infection." (PMID 36845118, 2023).
infection (continued). "MX1, OAS, IFIT1, and IFIT2 showed a significantly larger induction in the WT-infection compared to the ΔUL138STOP-infection either at 24 hpi for OAS or 48 hpi for MX1, IFIT1 and IFIT2." (PMID 37289831, 2023). "qPCR assays showed that Ptk2b deficiency significantly attenuated the mRNA levels of Ifnb1, Ifit1 and Cxcl10 stimulated by HSV1-GFP and VSVΔM51-GFP infection." (PMID 37989995, 2023). "In accordance with the in vivo results, SARS-CoV-2-∆8 infection induced higher expression levels of IFN-β and pro-inflammatory cytokines than SARS-CoV-2-WT at 24 hpi and lower levels of IFN-β, IFN-λ, and IFIT1 at 72 hpi." (PMID 37623322, 2023). "qRT-PCR assay showed that eight antiviral-related mRNA including IRF3, IRF7, IKKβ, TBK1, IFIT1, IFI44, MX1 and ISG15 displayed significantly stronger and quicker response at early infection under 20 °C." (PMID 37627029, 2023). "Quantitative PCR (qPCR) analysis showed that PTK2B knockdown significantly attenuated the transcriptional levels of antiviral genes such as IFNB1, IFIT1 and CXCL10 induced by HSV1-GFP infection or by transfection with human telomeric DNA (HT-DNA)." (PMID 37989995, 2023). "Interferon-stimulated genes such as Isg15, Isg56 (IFIT1), and Interferon-induced GTP-binding protein Mx1 (Mx1) were strongly induced following infection." (PMID 36851549, 2023). "We assessed IFIT1 and IFNB1 expression in HeLa cells in response to 5xSunTag-EMCV(LZn) infection using smFISH—a sensitive, single-cell method for analysis of gene expression." (PMID 37814072, 2023). "Compared to changes in inflammatory cytokine levels, ZBP1 knockdown only mildly attenuated the infection‐induced expression of IFNB and the interferon‐induced gene IFIT1 (Fig EV5F)." (PMID 36268590, 2022). "IFIT1 transcript was reduced, while IFIT2 was unchanged in WT infection compared to mock-infected control as shown in our previous work." (PMID 35758691, 2022). "The previous research reported that IFIT1, IFIT2, IFTI3, IFIT3, IFI44, HERC4, and OASL genes are antitumoral effects and modulated the inflammatory response in cancer and infection." (PMID 35941292, 2022). "In contrast, the BPH-1 cells are strong inducers of IFN-I at a high multiplicity of infection and respond to IFN-I after P/V/F mutant infection, with induction of three key ISGs (OAS2, IFIT1 and TLR3), indicating the establishment of an anti-viral state." (PMID 35631014, 2022). "There was higher expression of IFN-β, IFIT1, IFIT3, ISG15, and IRF7 mRNA in A549 XRN1 KO cells after 8 h of infection with various virus strains, including WSN (H1N1), PR8 (H1N1), CA04 (H1N1), and HK4801 (H3N2)." (PMID 34311580, 2021). "p62 knockdown significantly reduced levels of IRF7, ISG15, IFIT1, IFIT2, and IFIT3 genes, suggesting that p62 was required for maximal activation of the innate immune response during KSHV primary infection." (PMID 33414399, 2021). "Of note, infection of these cells with ZIKV also induced transcription of IFN, IFIT1, and inflammatory cytokine genes." (PMID 33658344, 2021). "ISGs and immune response genes such as IFIT1, IFIT2, IFIH1, MX1, MX2, and RSAD2 were highly down-regulated in response to all viruses at later time points of infection, confirming our transcriptome data." (PMID 33791243, 2021). "The principal effect of YTHDF3 depletion on the innate host response to PVSRIPO infection was dampened induction of ISGs (STAT1, MDA5, IFIT1, ISG15, OAS1)." (PMID 33849973, 2021). "Further RT-PCR analyses determined that the levels of IFNB1, IFIT2, IFIT1, TNF and the proinflammatory cytokines CCL20 and IL6 were enhanced by RTN3 knockdown during VSV infection, while the amplification of VSV was compromised." (PMID 34313226, 2021). "The impact of siMX1 and siIFIT1 was further evaluated by measuring ZIKV genome copies at 48 and 96 h post-infection and confirmed that MX1 and IFIT1 silencing only affected ZIKV RNA replication at the later time point of infection." (PMID 34079533, 2021).
infection (continued). "(F) RT-PCR analysis of IFNB1, IFIT2, IFIT1, TNF, IL6, and CCL20 mRNA levels in HEK293T cells transfected with HA-Ev or HA-RTN3 followed by infection with VSV-eGFP (MOI = 1) at the indicated timepoints." (PMID 34313226, 2021). "Other IFN-induced effector proteins with tetratricopeptide repeats (IFIT1-3, IFIT5) were 1.6–3.5-fold induced after infection and function in RNA degradation and inhibition of translation." (PMID 34777295, 2021). "Infection of HEp2 cells overexpressing IFIT1–3 or IFI44 individually with RSV, showed that the multiplicity rate of RSV was inhibited starting from 72 h post-infection (p < 0.01)." (PMID 33081322, 2020). "Upon fetal infection, a set of core responsive IFN-inducible genes (CXCL10, IFIH1, IFIT1, IFIT3, ISG15, and MX1) were strongly upregulated in both tissues." (PMID 33148169, 2020). "We found upregulated genes that were also upregulated following basolateral infection, such as CXCL2, CXCL3, CXCL10, IFNβ-1, IFNλ-1, -2, -3, endothelin 1 (EDN1) and IFIT-1, -2 and -3." (PMID 32872518, 2020). "We found that the expression levels of IRF-7, IFIT1, IFIT2, and RIG-I showed statistically significant differences after infection with hNS1-expressing recombinant viruses or aNS1-expressing recombinant viruses at certain time points." (PMID 31597767, 2019). "Silencing IFIT1 during KSHV lytic reactivation (left) as well as during de novo infection (right) increased the expression of the KSHV early lytic protein K-bZIP." (PMID 31059555, 2019). "In Ifit1-/- cells infected at a high multiplicity of infection, MNV-1 titres were slightly higher than wild-type cells at 6–8 hours post infection." (PMID 31372503, 2019). "Cortical neurons induce type I IFN after infection, respond to IFN treatment, and upregulate viperin and other ISGs (Mx1 and Ifit1)." (PMID 29544502, 2018). "By contrast, the upregulated IFIT1 and IFIT2 transcripts which began to rise only by 4 hours were refractory to the activity of incoming vhs and required active infection to be degraded (left-hand panel)." (PMID 30475899, 2018). "The expression levels of some ISGs (IFIT1, IFIT2, IFIT3) and proinflammatory cytokines (IL-6, IL-8) in DDX1-knockdown cells were analyzed after TGEV infection." (PMID 28848548, 2017). "Infection with either strain increased expression of ISGs (GBP1, IFIT1, IRF7) and reduced expression of lymphocyte related genes (CD3D, CD8A, ZAP70)." (PMID 28852031, 2017). "It revealed that both mouse and human responses along PC1 (the infection response) are largely driven by interferon-response genes (e.g. ISG15, IFIT1)." (PMID 27193691, 2016). "The expression of Interferon stimulated genes (IFIT1 and IFIT2) also reduced with progression of infection." (PMID 27282499, 2016). "Four ISGs, IFIT1, IFIT2, IFNβ, and OASL1, were analyzed following infection in the presence of DMSO or KPT-185." (PMID 27902702, 2016). "More importantly, the silencing of SNRNP200 in MDM decreases the induction of IFIH1 and IFIT1, and completely blocks IRF3 Ser386 phosphorylation within 3 hours post-infection." (PMID 27454487, 2016). "In all of the generated IFIT1-expressing bulk cell lines, individual cells demonstrated different levels of GFP expression upon infection with these viruses, additionally suggesting the dependence of virus replication on the level of IFIT1 expression." (PMID 25927359, 2015). "There was a relative decrease in the mRNA expression for TNF-α, IFN-κ, IFI16, IFIT1, MDA5, and RIG-I in the CPV-2 infected keratinocytes when compared to uninfected keratinocytes at 4 days post infection." (PMID 25025687, 2014). "In the present study, the IFN-stimulated genes (IFIT1, IFIT3, MX1, ISG15, OAS1, and IFI6) were dramatically increased at 16 h and 24 h post infection, which should trigger powerful antiviral functions." (PMID 23527143, 2013). "IFIT1 and DDX58 proteins increased from 24 to 48 hours post-infection while phosphorylated NFKBIA increased up to 32 hours post-infection in CTNNB1 knockdown cells." (PMID 23785285, 2013).
infection (continued). "Ifit1 (ISG56) is an ISG that is highly upregulated upon WNV infection, thus its absence from the infection-induced bioset was unexpected." (PMID 23300459, 2013). "In cell culture and mouse models of infection, WNV strongly induces Ifit1 gene expression in target cells via IFN-dependent and -independent signaling pathways." (PMID 22589727, 2012). "With the insertion of K1L and C7L, this response was tempered; infection with NYVAC-C-KC-ΔB8RΔB19R induced increased transcriptional levels of seven of the genes shown, relative to NYVAC-C-KC (IFI35, IFI44, IFI44L, IFIT1, IFIT3, IFITM1, and IFITM2)." (PMID 22096477, 2011). "At 16 and 48 hr post-infection, WT HIV-1 increased IFIT1 mRNA levels in infected iDCs 44- and 40-fold, respectively, relative to mock infection." (PMID 21504576, 2011). "Consistent with this, we recently documented a paucity of type I IFN-dependent ISG expression (e.g., IFIT-1, ISG15) within the liver of HAV-infected chimpanzees during the first weeks of infection despite high viral RNA copy numbers." (PMID 21931545, 2011). "The results showed that SVA infection could significantly downregulate the expression of IFNB, IFIT2, IFIT1 and OAS1 induced by poly (I:C), but this inhibitory effect was weakened in VP2 knockdown cells." (PMID 41319264, 2026). "In addition, expression of the protein-coding genes CXCL10, IFIT1, NCOA7, IFIT2, SIX3, and RPSA was increased during infection." (PMID 40510596, 2025). "In the brain, infection with Bov342 induced the expression of type-I (Ifna5, Ifnb), -II (Ifng), and -III (Ifnl2) interferons (IFN), interferon stimulated genes (ISGs) (Isg15, Ifit1, Mx1, Oas1), and pro-inflammatory cytokines (Il1b, Il6, and Tnfa) at endpoint." (PMID 40410375, 2025). "We propose that the virus has evolved differing sensitivity of viral mRNAs to IFIT1 as a mechanism to regulate viral protein production in response to IFN and may be important in allowing the virus to establish prolonged/persistent infections." (PMID 40146622, 2025). "In addition to type I IFNs, mRNA expression of proteins related to antiviral responses, such as CXCL10, IFIT1, and CCL5, are upregulated after infection." (PMID 39601535, 2025). "Protein lysates collected after interferon pre-treatment, but prior to infection, showed decreased levels of representative ISGs IFIT1 and MX1 upon CPSF6 knock-out, though not to the same extent as observed upon IFNAR1 knock-out." (PMID 41385587, 2025). "Early acute infection and A549 infected cells shared 150 upregulated genes including ATF3, a stress induced transcription factor, as well as other genes involved in the innate immune response such as MX1, DDX58/RIG-I, IFIT1, IFIT2, DHX58/MDA5, and OASL." (PMID 39065267, 2024). "PHEV significantly upregulated ISG15 expression (>1.5 log2FC) at all three time points, and it appears ISG15 does interact with HERC5, IFIT1, PKR, TRIM25, STAT1, and USP18, as their expression was also enhanced (>1.0 log2FC) at various timepoints during ALI-PRECs infection." (PMID 38932231, 2024). "Taken together, upregulation of neither LGALS3BP nor IFIT1 mRNA was detectable in Calu-3 cells after infection with SARS-CoV-2, in line with SARS-CoV-2’s ability to prevent efficient recognition by cell-intrinsic innate immunity." (PMID 37162650, 2023). "We consider that the moderate increase of IFIT-1 mRNA at 24 h post infection in SARS-CoV-2 infected Calu-3 cells results from an outlying data point rather than representing a genuine upregulation of IFIT-1 mRNA." (PMID 37162650, 2023). "In the context of infection, ORF4a antagonizes IFN production and signaling, as A549DPP4 cells infected with a recombinant MERS-CoV-Δ4a showed increased mRNA expression levels of interferon lambda (IFNL1) and ISGs OAS2 and IFIT1." (PMID 37197199, 2023).
infection (continued). "Furthermore, the temporal expression profiles of eight selected antiviral-related mRNA including IRF3, IRF7, IKKβ, TBK1, IFIT1, IFI44, MX1 and ISG15 were detected by qRT-PCR, which showed a significantly stronger response at early infection under 20 °C." (PMID 37627029, 2023). "We observed a NS1 dosage-dependent host response for genes involved in the inflammatory response (IL-6, IFNB1) and interferon stimulation (IFIT1, MX1, ISG15), with the IAV-NS1-T infection generating an intermediate phenotype at both the transcript and at the protein levels." (PMID 37876781, 2023). "Notably, multiple antiviral proteins were also dramatically decreased in PAMs during the PRRSV-ADE infection, including ISG15, ISG20, IFIT1 (ISG56), IFIT2 (ISG54), IFIT3 (ISG60), IFIT5 (ISG58), OAS1, Mx1, RSAD2, TRIM22, TRIM25 and TRIM34, except for TRIM52." (PMID 36680075, 2022). "As expected, infection with the LAI virus, which was prepared using method A and induced high levels of IFN-I in the supernatant, upregulated the expression of many ISGs, such as IFIT1 and OAS1." (PMID 34844429, 2021). "Upon infection of these cells with ZIKV for 24 and 48 h, we observed a decreased antiviral response, as evidenced by significantly lower mRNA levels of IFN-β and the ISGs IFIT1 and Mx1." (PMID 33658344, 2021). "In response to R. equi infection, while STING KO macrophages induced Tnfa to comparable levels as control macrophages (expressing a GFP-targeting guide RNA), they failed to induce Ifnb, Isg15, or Ifit1 at 4- or 8h post-infection." (PMID 34473814, 2021). "We observed a temporal increase in expression of the Type I IFN response genes Il1rn, Ifit2, Ifit1 and Ifih1 (data not shown) upon infection." (PMID 34603294, 2021). "IFIT1 inhibits translation at the initiation stage by competing with the cap-binding initiation factor complex, eIF4F, restricting infection by certain viruses that possess “nonself” cap0-mRNAs." (PMID 33454014, 2020). "In contrast, IFIT1 was upregulated by IFN-α in A549/Npro cells but was not upregulated by infection of these cells by PIV5-VΔC vM2." (PMID 32295916, 2020). "Our main findings were: 1) the host immune response was initiated only in fetuses with detectable levels of PRRSV; 2) upon infection of fetal thymus, a set of core responsive IFN-inducible genes (CXCL10, IFIH1, IFIT1, IFIT3, ISG15, and MX1) were strongly upregulated in both tissues." (PMID 33148169, 2020). "Moreover, similar expression levels for several Interferon-stimulated genes (ISGs), namely Ifit1, Ifi44, Usp18, Ifit3 and Irf7, were observed in the livers of Ctrl and RKV-supplemented mice at various time points after infection." (PMID 33294789, 2020). "For example, and as confirmed in this study, IFIT1 strongly restricts PIV5 infection, yet it has reduced activity against HPIV2 and likely no activity against HPIV3 or human respiratory syncytial virus." (PMID 32423918, 2020). "In the IFIT1‐luc cells, ∆CA‐SP1 mutation did not impact infection levels (Fig EV2A–C) and neither did ruxolitinib treatment (Fig EV2C)." (PMID 32852081, 2020). "IFIT1 and OAS2 genes were induced by P/V-CPI- infection of control cells." (PMID 31083335, 2019). "Hepatocytes clustered by the infection status of the mice, and we confirmed hepatocyte-intrinsic repression of Ass1 and Otc upon infection, which inversely correlated with expression levels of the ISG Ifit1 on the single-cell level." (PMID 31784108, 2019). "These nPro/HFs and V/HFs were recently utilized, alongside IRF3 KO CRISPR/Cas9 HFs, to demonstrate that expression of viperin, ISG15, IFIT1, IFIT2, IFIT3, Mx1, and Mx2 mRNA during infection with HCMV can be induced in an IRF3-dependent, STAT1-independent manner." (PMID 31921100, 2019).